RMC1 (regulator of MON1-CCZ1)
Description:
Component of the CCZ1-MON1 RAB7A guanine exchange factor (GEF). Acts as a positive regulator of CCZ1-MON1A/B function necessary for endosomal/autophagic flux and efficient RAB7A localization.
Synonyms: Mic-1; C18orf8; MIC1; WDR98; HsT2591
Tractability: PROTAC: ubiquitination databases record sites on it.
Gene: Protein-coding gene on chromosome 18 (23,503,483 to 23,531,822, forward strand). Ensembl gene ENSG00000141452.
Subcellular location: Lysosome membrane; Late endosome membrane
Subcellular location (Human Protein Atlas): Nucleoplasm
Gene Ontology:
Molecular function: protein binding; guanyl-nucleotide exchange factor activity
Biological process: regulation of autophagy
Cellular component: late endosome; late endosome membrane; lysosomal membrane; Mon1-Ccz1 complex
Genetic constraint (gnomAD): Loss-of-function variants: 34 observed, 79.21 expected, observed/expected ratio (o/e) 0.43, 90% interval 0.33 to 0.57. The upper end of that interval is the gene's LOEUF score, 0.57, which puts it in group 2 of 6, group 1 being the genes least tolerant of losing a copy. Missense variants: 571 observed, 684.35 expected, observed/expected ratio (o/e) 0.83, 90% interval 0.78 to 0.89. Synonymous variants: 259 observed, 252.86 expected, observed/expected ratio (o/e) 1.02, 90% interval 0.93 to 1.13.
Homologues: Orthologues: macaque RMC1 (99% identical), chimpanzee RMC1 (99% identical), guinea pig RMC1 (95% identical), dog RMC1 (95% identical), rat Rmc1 (95% identical), mouse Rmc1 (95% identical), pig RMC1 (94% identical), rabbit RMC1 (91% identical), tropical clawed frog rmc1 (83% identical), zebrafish rmc1 (50% identical), Drosophila melanogaster Bulli (36% identical), Caenorhabditis elegans Y50D4A.4 (29% identical).
Diseases named in the same sentence as RMC1 in open-access papers:
RMC1 is named in the same sentence as 14 diseases in open-access papers, as found by Europe PMC text mining. Sharing a sentence is not in itself a finding about the gene and the disease. The quoted sentences say what the papers report.
colon cancer (1 paper, 2024). "The genes analyzed in this study, Chromosome 18 open reading frame 8 protein (C18ORF8/RMC1) and a disintegrin and metalloproteinase with thrombospondin motifs 9 (ADAMTS9) have been highlighted for their association with colon cancer tumors." (PMID 39058128, 2024).
Hyperglycemia (1 paper, 2012). An increased concentration of glucose in the blood. "We observed an enhanced mitochondrial staining as well as the formation of larger mitotracker puncta, indicating that autophagy/mitophagy may occur in rMC1 under chronic hyperglycemia." (PMID 22474421, 2012). "Therefore, we undertook a series of experiments to examine the temporal response of rMC1 to chronic hyperglycemia in culture." (PMID 22474421, 2012). "Therefore, we hypothesize that a cell survival program is evoked under chronic hyperglycemia and oxidative stress in rMC1." (PMID 22474421, 2012).
Parkinson disease (1 paper, 2025). A progressive degenerative disorder of the central nervous system characterized by loss of dopamine producing neurons in the substantia nigra and the presence of Lewy bodies in the substantia nigra and locus coeruleus. "For the Parkinson’s disease model, RMC1 was the top predictive gene with a strong importance score of 0.73." (PMID 41296471, 2025).
retinopathy (2 papers, 2022 to 2025). "To investigate AAV2-shmTOR’s impact on atypical inflammation in these conditions, we employed an in vivo model of oxygen-induced retinopathy and an in vitro model using rMC1 Müller cells." (PMID 39897639, 2025).
RMC1 also shares sentences with these, for which no sentence is quoted: cancer (4 papers); diabetes (3); cerebral malaria (1); fibrosarcoma (1); glaucoma (1); infection (1); neuropathy (1); Niemann-Pick disease (1); Niemann-Pick disease, type C1 (1); Obesity (1).